EZH2 (enhancer of zeste 2 polycomb repressive complex 2 subunit)
Diseases named in the same sentence as EZH2 in open-access papers (continued):
Sharing a sentence is not in itself a finding about the gene and the disease.
melanoma (continued). "This role for ATRX could presumably account for the upregulation of EZH2 target genes in melanoma and the increased expression of the X chromosome-related genes, such as KDM6A." (PMID 32731355, 2020). "This suggested that the level of EZH2 and its demethylase KDM6A may play a pivotal role in regulating genes associated with immune evasion in melanoma." (PMID 32731355, 2020). "No predictive value for therapeutic response to anti-PD-1 therapy could be found for H3K27me3 or EZH2 expression on melanoma cells." (PMID 32041674, 2020). "The observation that EZH2 and H3K27me3 are predominantly expressed at the IF supports the hypothesis of an invasive, dedifferentiated EZH2 or H3K27me3 expressing melanoma cell phenotype, though." (PMID 32041674, 2020). "Importantly, GSK503 an inhibitor of the methyltransferase activity of EZH2, restored tumor immunogenicity and T-cell infiltration and suppressed melanoma growth upon immunotherapy." (PMID 32042336, 2020). "In control melanoma model mice, melanoma-positive lymph nodes and distant metastasis in the lung are consistently developed; while in EZH2 conditional knockout mice, there is a significant reduction of lymph node metastasis and a virtual absence of lung metastasis." (PMID 32723346, 2020). "The same study identified functionally distinct suppressors of melanoma as targets of EZH2." (PMID 33024276, 2020). "Another important finding of our study reported that the overexpression of EZH2 further accelerated the H3K27 trimethylation which suppress the oxidative stress as well as apoptosis in melanoma cell and stimulated the viability of melanoma cell via inhibition of CDKN1C." (PMID 32308561, 2020). "29/44 (66%) of melanomas showed H3K27me3 expression, and 6/44 (14%) showed EZH2 expression." (PMID 32041674, 2020). "Consequently, our findings demonstrate that the elevation of lncRNA GAS5 upregulates CDKN1C to suppress the viability of melanoma cells and induce cell apoptosis as well as oxidative stress by inhibiting EZH2 expression and H3K27 trimethylation." (PMID 32308561, 2020). "Increased expressions of EZH2 and H3K27me3 were detected in multiple tumors, including melanoma." (PMID 32041674, 2020). "Another interesting finding of our study was the specific heterogeneous distribution pattern of H3K27me3 and EZH2 immunohistochemical expression profile in many melanoma samples, as stronger expression was localized at the IF compared with the inner tumor mass." (PMID 32041674, 2020). "Several studies have shown an important role for EZH2 in melanoma initiation and progression." (PMID 33024276, 2020). "Furthermore, EZH2 inhibition can increase the cytotoxicity of human effector T cells in vitro and improve the efficacy of anti-CTLA-4 therapy in murine bladder cancer and melanoma as anti-CTLA-4 increases the expression of EZH2 in peripheral T cells." (PMID 32723346, 2020). "Moreover, EZH2 overexpression has been documented in several human cancer types, including liver, lung, bladder, breast, melanoma, and colorectal cancers." (PMID 32906688, 2020). "EZH2 is overexpressed in many cancers, such as breast, bladder, melanoma and prostate cancer." (PMID 32708698, 2020). "Furthermore, in melanoma, histone methyltransferase Ezh2 regulates the T-cell resistance against immunotherapy." (PMID 32344837, 2020). "The conclusion could be reached that silenced EZH2 or overexpressed CDKN1C could block the cell viability of melanoma and accelerate oxidative stress and cell apoptosis of melanoma." (PMID 32308561, 2020). "In subsequent experiments, we further identified that lncRNA GAS5 could upregulate CDKN1C to accelerate oxidative stress and apoptosis of melanoma cells and inhibit its viability by blocking EZH2 and H3K27 trimethylation." (PMID 32308561, 2020).
melanoma (continued). "This study proposed a potential therapeutic target lncRNA growth arrest-specific transcript 5 (GAS5) for melanoma, due to its crucial role in oxidative stress and apoptosis of melanoma cells by regulating the enhancer of zeste homolog 2 (EZH2)-mediated CDKN1C expression." (PMID 32308561, 2020). "The combined use of a DNMTi and an EZH2 inhibitor (EZH2i) may lead to expression of tumor suppressor genes and increased immune responses to effectively treat melanoma." (PMID 32751889, 2020). "In addition to EZH2 activation, other PcG proteins are frequently deregulated in melanoma, including the chromatin remodelling complex SWI/SNF and the chromatin assembly factor-1 (CAF-1)." (PMID 31861757, 2019). "In addition, inhibition of NFATc2 by AM404 or zoledronic acid, or the GSK-3β inhibitor AR-014418 in association with the EZH2 inhibitor GSK126-induced significant anti-proliferative and pro-apoptotic effects on melanoma cell lines." (PMID 30710146, 2019). "The 3-deazaneplanocin A (DZNep), a small molecule inhibitor of Ezh2, decreases global H3K27 trimethylation, and its overexpression is associated with aggressiveness of several cancers such as prostate, breast, and bladder, as well as melanoma." (PMID 31320814, 2019). "Melanoma cell lines belonging to distinct mutational groups (BRAF-mutant, NRAS-mutant, or wild type for both BRAF and NRAS) co-expressed NFATc2 and EZH2 supporting the rationale for testing the potential anti-tumor effects of pharmacological co-targeting." (PMID 30710146, 2019). "In addition, aggressive melanoma cells have excessive levels of H3K27me3 accompanied by EZH2 overexpression, in which EZH2 controls melanoma progression and metastasis by silencing tumor suppressors." (PMID 30466474, 2018). "Protein levels of EZH2 increase incrementally from benign nevi to cutaneous malignant melanoma, which also suggests that EZH2 may play a role in the pathogenesis and tumorigenesis of melanoma." (PMID 30466474, 2018). "Interestingly, this study showed that NIK protein was stabilized in melanoma cells and is critical for EZH2 expression." (PMID 29874793, 2018). "Furthermore, in melanomas, EZH2 similarly repressed AMD1 gene expression (a protein involved in polyamine synthesis), leading to increased levels of SNAI1, ZEB1, and TWIST1, and to increased invasion and metastasis, both in vitro and in vivo." (PMID 34991274, 2018). "Using both an RNA interference and preclinical drug GSK305 to target EZH2, they showed that EZH2 could be a promising therapeutic target in the treatment of melanoma patients." (PMID 28359267, 2017). "Conversely, constitutive BRN2 overexpression was also performed in these same cell lines and revealed a commensurate increase in both NFIB (3.8, 3.7, 2.4 fold respectively) and EZH2 (2.5, 2.3, 2.6 fold respectively) expression across all three melanoma cell lines." (PMID 28119061, 2017). "The mean age (P = 0.312) and gender (P = 0.553) were not significantly different between melanoma patients harbouring BRAF V600E mutation with or without EZH2 gain." (PMID 29202777, 2017). "Given the obvious cell-cycle arrest and apoptosis induction was observed after combined treatment, BRAF and EZH2 may cooperate in accelerating cell-cycle progression and inhibiting apoptosis to promote melanoma cell growth." (PMID 29202777, 2017). "Moreover, recent studies have shown that EZH2 also plays a critical role in the proliferation and survival of melanoma." (PMID 29202777, 2017). "While our study reveals the regulation of the EZH2 chromatin modifying enzyme by NFIB is a key conduit of this effect in melanoma cells, it remains to be determined if a similar epigenetic axis is governed via an NFIB-EZH2 axis in other tumour types to drive invasion and metastasis." (PMID 28119061, 2017).
melanoma (continued). "Indeed, as reported by others, TNF can trigger melanoma dedifferentiation as well as expression of the Ezh2 histone methyltransferase and the CD73 ectonucleotidase in melanoma cells, all of those events conferring resistance to immunotherapy." (PMID 29273790, 2017). "Apart from altered DNA-methylation patterns and microRNA deregulation, histone modifying enzymes such as histone deacetylases (HDAC) and polycomb repressive complex (PRC) members EZH2, JARID2, and BMI1, have been implicated in melanoma growth, epithelial-mesenchymal transition (EMT), and metastasis." (PMID 28978033, 2017). "EZH2 has been shown to play roles in melanoma pathogenesis via silencing of tumor suppressors." (PMID 28400597, 2017). "In univariate Cox analysis, the clinicopathologic factors, such as TNM stage and EZH2 amplification, may be of prognostic significance for melanoma patients; For multivariate Cox regression assay, TNM stage is independent prognostic factors for OS." (PMID 29202777, 2017). "Similarly, in multiple melanoma cell lines which have lost miR-31 expression due to promoter hypermethylation, miR-31 pre-treatment results in decreased expression of Src and EZH2." (PMID 26734997, 2016). "Moreover, the authors demonstrated that down-regulation or inhibition of EZH2 in tumor-specific T cells increases the tumor burden and the metastatic potential in mouse models of ovarian cancer and melanoma, respectively." (PMID 27793053, 2016). "The epigenetic modifier EZH2 can be targeted with the specific inhibitor GSK126 in melanoma." (PMID 27095580, 2016). "In addition, we have identified a set of SCNAs, including amplification of BRAF and EZH2, in thick melanomas that subsequently developed metastasis." (PMID 27095580, 2016). "In addition, we have identified a set of SCNAs, including amplification of BRAF and ofthe epigenetic modifier EZH2, that are specific for the group of thick melanomas that developed metastasis during the follow-up." (PMID 27095580, 2016). "In addition, GSK126 can target mutant EZH2 effectively in melanoma cells by de-repressing tumor suppressor genes and subsequently inhibiting tumor growth." (PMID 27793053, 2016). "Spheroid models were used to test the effectiveness of EZH2 inhibition in 3D melanoma cultures." (PMID 26304929, 2015). "While the 3D culture morphology changes caused by EZH2 in BEAS-2B epithelial cells can be attributed to the prominent EMT signature (including suppression of the master regulator E-Cadherin), A375 melanoma cells express very little to undetectable levels of E-Cadherin (not shown)." (PMID 25671303, 2015). "Despite the fact that GOF mutations are selected for within melanoma, the expression of EZH2 GOF mutants (Y641F, Y641N) gave no growth advantage to A375 cells grown under standard tissue culture conditions." (PMID 25671303, 2015). "EZH2 plays a main role on the maintenance of cellular epigenetic integrity, being highly relevant on human BC, among other tumors such as prostate, breast, ovarian, renal carcinoma, lung, liver, brain, gastric, esophageal, pancreatic, or melanoma." (PMID 26580594, 2015). "In addition the importance of EZH2 dysregulation in melanoma is supported by its amplification in 5% of melanoma samples and increased mRNA expression in 14% of cases in the TCGA dataset." (PMID 26304929, 2015). "Furthermore, the aggressive 3D morphology of EZH2 GOF-expressing melanoma cells (both endogenous and ectopic) was attenuated by EZH2 catalytic inhibition." (PMID 25671303, 2015). "Further studies are needed to define the basis for sensitivity of EZH2 WT melanoma to EZH2 inhibition and whether gene signatures can be used to predict melanomas that are sensitive to EZH2 inhibitors." (PMID 26304929, 2015). "A growing body of evidence supports a role for EZH2 in the pathogenesis of melanoma." (PMID 26304929, 2015).
melanoma (continued). "Further evidence for the importance of EZH2 in melanoma came from knockdown studies of EZH2 that resulted in reduced proliferation, restoration of a senescent like phenotype and reduced growth of xenografts in mice, due to the reactivation of CDKN1A/p21 tumor suppressor." (PMID 26304929, 2015). "Although miR-31 has been shown to act as either an oncomiR or tumor suppressor in various tumor types, in this study we clearly establish miR-31 as a tumor suppressor, demonstrate that it targets multiple oncogenes such as SRC, MET, NIK and RAB27a and regulates the expression of EZH2 in melanoma." (PMID 22948084, 2012). "Downregulation of EZH2 may represent an additional tumor suppressive role for miR-31 since EZH2 plays a pro-tumorigenic role in melanoma." (PMID 22948084, 2012). "However, the expression status and mechanisms of EZH2 overexpression are also poorly understood in melanoma." (PMID 22948084, 2012). "Taken together, these data suggests EZH2 as a highly expressed histone methyltransferase which might be playing a role in melanoma progression leading to poor survival." (PMID 22948084, 2012). "However, melanoma cell lines displayed overexpression of EZH2 mRNA and protein and notably the EZH2 mRNA and protein were highly correlated (Spearman r= 0.88, p= 0.0003)." (PMID 22948084, 2012). "Therefore, we aimed to examine separately the effect of two well-established melanoma drivers on MPNST cells: PRC2 activity (‘Ezh2 GOF’) and canonical Wnt signaling (‘Wnt GOF’), with the aim to specifically assess the transdifferentiation/plasticity potential of this tumor type." (PMID 41063628, 2025). "Consequently, inhibition of EZH2 or HDAC3 could re-establish chemokine expression in IκBζ-overexpressing melanoma cells, thereby validating HDAC3 and EZH2 as critical effectors downstream of IκBζ." (PMID 40562773, 2025). "No clinical trials have yet reported the efficacy of tazemetostat in patients with melanoma, but preclinical studies have suggested EZH2-targeted therapies may interfere with melanoma progression and metastasis and could be a target for combinations with either ICI or BRAF-targeted therapy." (PMID 39984702, 2025). "The EZH2 mutational status may indeed impact sensitivity to BRAF inhibition, providing a potential explanation for the development of resistance to BRAF inhibition in certain melanoma cases." (PMID 39304771, 2024). "PVT1 may also influence melanoma by regulating MIR200C via EZH2." (PMID 39372928, 2024). "Thus, the reversal of an abnormal epigenetic landscape appears to be a promising therapeutic approach, such as in the case of EZH2 (Enhancer of Zeste Homologue 2; a histone methyltransferase) over-expression and its role in melanoma development and progression." (PMID 38473991, 2024). "Furthermore, EZH2 depletion activates p21 and induces senescence in melanoma." (PMID 38804044, 2024). "Mechanisms of post-translational EZH2 regulation in melanoma are largely unknown." (PMID 36906655, 2023). "Therefore, we wondered whether targeting EZH2 might represent a new therapeutic option in melanomas resistant to BRAF inhibitors." (PMID 36768289, 2023). "In contrast to this, we observed synergistic effects of the combined inhibition of BRAF and EZH2 only on melanoma cells resistant to vemurafenib, whereas in susceptible melanoma cells, we observed no additional benefit compared to treatment with vemurafenib alone." (PMID 36768289, 2023). "Enhancer of zeste 2 polycomb repressive complex 2 subunit (EZH2), which has histone methyltransferase activity, is highly expressed and installs the H3K27me3 histone mark at tumor suppressor genes, thereby inhibiting their expression to drive the development and metastasis of melanoma." (PMID 37760992, 2023). "Therefore, combined treatment with EZH2 and MEK1/2 inhibitors may provide a novel promising therapeutic strategy for NRAS-mutated and wild-type melanomas, as these types of melanomas are resistant to BRAF inhibitors." (PMID 37325482, 2023).
melanoma (continued). "Therefore, we wondered whether EZH2 could serve as a therapeutic target in melanomas resistant to BRAFi." (PMID 36768289, 2023). "In the clinic, melanoma patients who were treated with immune checkpoints inhibitors targeting PD-1 (Programmed cell Death protein 1), PD-L1 (Programmed cell Death protein ligand 1) and CTLA-4 (Cytotoxic T-Lymphocyte-associated antigen 4) can become resistant and harbored an upregulated EZH2." (PMID 36230787, 2022). "Moreover, in different cancer types, including melanoma and ovarian, and in PCa mouse models, it has been shown that EZH2 inhibition leads to an increase in the intra-tumoral trafficking of activated CD8+ T-cells, and this recruitment is mediated by CXCL10-CXC chemokine receptor 3 (CXCR3)." (PMID 36135315, 2022). "It was shown that IFN signaling is a target of EZH2 suppression in cancer: EZH2 represses IFNγ target genes in prostate, colorectal, and melanoma cancer cells, while pharmacological inhibition of EZH2 in melanoma results in the upregulated profile of IFNγ and IFN-α downstream targets." (PMID 36463299, 2022). "Hence, it is suggested that targeting EZH2, with a highly selective inhibitor alongside with immunotherapy could represent a good combinatory therapeutic strategy to tackle melanoma." (PMID 36230787, 2022). "Therefore, EZH2 inhibitors might be clinically available to confirm the anti-tumor action against melanomas." (PMID 35163049, 2022). "Also, impaired EZH2 expression in T cells resulted in poor tumor control in ovarian cancer and melanoma, highlighting the important role of Ezh2 in maintaining the survival of effector T cells and T cell polyfunctional cytokine expression as well as the formation of memory precursor T cells." (PMID 33403469, 2021). "In addition, alterations in epigenetic regulators like EZH2, ARID2, and IDH1/2, as well as genomic instability caused by mutations in the DNA damage response (DDR) genes, can lead to the altered transcription of key gene regulators in melanomas." (PMID 34831002, 2021). "Additionally, T cell accumulation in the tumor during anti-CTLA-4 or IL-2 immunotherapy leads to an increase in EZH2 expression in melanoma cells, which further decreases their immunogenicity and antigen presentation, thus contributing to intrinsic resistance to these immunotherapies." (PMID 34944799, 2021). "Notably, inhibition of EZH2 expression has been associated with the release of apoptosis-inducing factor (AIFM1) from mitochondria and the induction of caspase-independent apoptosis in human melanoma cell lines." (PMID 34575678, 2021). "Later on, Kampilafkos at al. observed that H3K4me2 and H3K27me3 levels were lower in metastatic compared to primary melanomas and that combined IHC analysis of H3K4me2, H3K27me3, and EZH2 may help identify cancer cells with stem cell-like behaviors, particularly at the invasion front of CM." (PMID 34575678, 2021). "In addition, it is worth noting that mutations also occur in the EZH2 gene in approximately 3% of melanomas, and furthermore that EZH2 has been shown to cooperate with DNA methylation changes to down-regulate key tumour suppressors and interferon gene signatures." (PMID 34680938, 2021). "Furthermore, the authors of this study demonstrated that EZH2 inhibition could restore tumor immunogenicity and T-cell infiltration and suppress melanoma growth upon re-challenging with immunotherapy." (PMID 34440824, 2021). "Likewise, the miR-211 expression was reduced by EZH2-mediated methylation in malignant melanoma, and overexpression of EZH2 significantly decreased miR-193a expression in OC, which was in compliance with the observed mechanism of EZH2-mediated methylation in our study." (PMID 33292225, 2020). "Thus here we may suggest, that in the future study, a larger cohort of clinical samples should be included in the research to further determine the underlying mechanism of lncRNA GAS5, EZH2, and CDKN1C in melanoma." (PMID 32308561, 2020).